TRAV20 (T cell receptor alpha variable 20)
Description:
V region of the variable domain of T cell receptor (TR) alpha chain that participates in the antigen recognition. Alpha-beta T cell receptors are antigen specific receptors which are essential to the immune response and are present on the cell surface of T lymphocytes. Recognize peptide-major histocompatibility (MH) (pMH) complexes that are displayed by antigen presenting cells (APC), a prerequisite for efficient T cell adaptive immunity against pathogens. Binding of alpha-beta TR to pMH complex initiates TR-CD3 clustering on the cell surface and intracellular activation of LCK that phosphorylates the ITAM motifs of CD3G, CD3D, CD3E and CD247 enabling the recruitment of ZAP70. In turn ZAP70 phosphorylates LAT, which recruits numerous signaling molecules to form the LAT signalosome. The LAT signalosome propagates signal branching to three major signaling pathways, the calcium, the mitogen-activated protein kinase (MAPK) kinase and the nuclear factor NF-kappa-B (NF-kB) pathways, leading to the mobilization of transcription factors that are critical for gene expression and essential for T cell growth and differentiation. The T cell repertoire is generated in the thymus, by V-(D)-J rearrangement. This repertoire is then shaped by intrathymic selection events to generate a peripheral T cell pool of self-MH restricted, non-autoaggressive T cells. Post-thymic interaction of alpha-beta TR with the pMH complexes shapes TR structural and functional avidity.
Synonyms: TCRAV20S1; TCRAV30S1
Gene: T-cell receptor variable (V) gene on chromosome 14 (22,040,594 to 22,041,153, forward strand). Ensembl gene ENSG00000211800.
Subcellular location: Cell membrane
Gene Ontology:
Biological process: response to bacterium
Cellular component: plasma membrane
Homologues: Orthologues: chimpanzee TRAV20 (80% identical), macaque TRAV20 (78% identical). Paralogues in human: TRAV7 (54% identical), TRAV21 (49% identical), TRAV36DV7 (49% identical), TRAV39 (48% identical), TRAV6 (46% identical), TRAV24 (44% identical), TRAV10 (43% identical), TRAV17 (42% identical), TRAV13-1 (39% identical), TRAV25 (39% identical), TRAV27 (38% identical), TRAV34 (38% identical), and 11 more.